ENSG00000212279
Synonyms: LOC124900366
Gene: Small nucleolar RNA gene on chromosome 15 (74,490,959 to 74,491,028, reverse strand). Ensembl gene ENSG00000212279.
Gene Ontology:
Biological process: RNA processing
Cellular component: nucleolus
Homologues: Orthologues: zebrafish snord80.1 (54% identical), zebrafish snord80.2 (54% identical). Paralogues in human: SNORD77B (80% identical).